FTO (FTO alpha-ketoglutarate dependent dioxygenase)
Diseases named in the same sentence as FTO in open-access papers (continued):
Sharing a sentence is not in itself a finding about the gene and the disease.
cancer (continued). "Meanwhile, our findings provided a novel and essential evidence that the crosstalk between lncRNA and m6A modifications especially caused by FTO regulated cancer progression and metabolism." (PMID 37840133, 2023). "Fat-mass and obesity-associated protein (FTO), which was the first discovered m6A demethylase, is involved in the regulation of adipocyte differentiation and cancer cell proliferation via the regulation of m6A modifications." (PMID 35568876, 2022). "The FTO variant (rs8047395) was also mapped with tumors of central nervous system or other cancers, as well as bone mineral density." (PMID 36778599, 2022). "Several reports have indicated that the expression change of FTO is associated with the occurrence of various cancers through stimulating cellular metabolism." (PMID 36672827, 2022). "On the contrary, recent studies reported that there is an association between variants of FTO including rs8050136, rs9939609, rs1477196, rs1121980, rs6499640, rs17817449, rs8047395, rs7206790 and rs11075995 polymorphisms and the risk of cancers." (PMID 36403211, 2022). "Several single-nucleotide polymorphisms (SNPs) in the FTO gene which located in a linkage disequilibrium block is predicted to be link with many cancers." (PMID 35422475, 2022). "Fat mass and obesity-associated protein (FTO) regulates critical pathways in various diseases, including malignant tumours." (PMID 36358640, 2022). "As the first identified demethylase of mRNA m6A modification, FTO with single nucleotide polymorphism (SNP) is associated with cancer susceptibility and tumorigenesis." (PMID 35524932, 2022). "The association between the most typical FTO SNP (rs9939609) and several cancers such as renal, lung, breast, pancreas, endometrial and prostate cancer were frequently reported." (PMID 36403211, 2022). "Fat mass and obesity-associated protein (FTO) is a demethylase and plays a vital role in various cancers." (PMID 37529797, 2022). "FTO, as the first identified m6A RNA demethylase, has been widely known to be implicated in cancer progression and clinical outcomes." (PMID 35211409, 2022). "This study enhances our understanding of the interaction between genetic susceptibility and dietary intake on cancer risk through assessing dietary intake, cancer risk and FTO polymorphism." (PMID 36403211, 2022). "Epidemiological studies also show that FTO SNPs is strongly associated with increased risk of various cancers." (PMID 35784761, 2022). "Demethylase fat mass and obesity-associated protein (FTO) is an m6A eraser, which plays a vital role in the progression of various cancers." (PMID 37529797, 2022). "Dysregulation of m6A erasers have been found too associated to cancer risk, in fact FTO polymorphisms have been known to be associated to several human disorders including increased risk of cancer for decades." (PMID 33461542, 2021). "The aberrant expression of fat mass and obesity-associated protein (FTO) has been confirmed to be associated with a variety of cancers and participates in the regulation of multiple biological behaviours." (PMID 34725345, 2021). "Given the essential role of FTO in development of some cancers and drug resistance, we evaluated the association with risk of PTC in Iranian patients." (PMID 34837923, 2021). "Taken together, these results suggested that FTO is positively associated with OSCC acquisition of cancer stemness and chemoresistance to cisplatin." (PMID 34378866, 2021). "The association between polymorphisms of the FTO gene and the clinical implications of multiple human cancer types has been reported previously." (PMID 33634966, 2021). "Nevertheless, FTO single nucleotide polymorphisms have been also found to be associated with other cancers." (PMID 34207299, 2021). "As a key demethylase, FTO regulates the stability of cellular mRNA by removing mA residues in mRNA, and it has been shown to be related to the risk of cancer." (PMID 34499008, 2021).
cancer (continued). "Later, FTO was found to be highly expressed in cancers and correlate with the risk of various human cancers." (PMID 34076564, 2021). "On the other hand, the substantial role of FTO in cellular metabolism is also considered as an influential factor directly associated with the pathogenesis of cancer." (PMID 33634966, 2021). "Previous studies demonstrate a strong association between up-regulation of FTO and various cancers, including breast, prostate and kidney." (PMID 32299393, 2020). "Studies on the role of fat mass and obesity-associated protein (FTO), a 2-OG- and iron-dependent m6A RNA demethylase, in cancer are rapidly accumulating." (PMID 33142830, 2020). "Low levels of ALKBH5 and FTO mRNA were associated with reduced overall as well as cancer-specific survival after nephrectomy." (PMID 33364952, 2020). "To date, it has been studied that variants of FTO rs9939609, rs8050136, rs1477196, rs6499640, rs1121980, rs17817449, rs11075995, rs8047395, and rs7206790 have an association with a higher risk of cancers (Hernández-Caballero and Sierra-Ramírez, 2015)." (PMID 33304380, 2020). "This study was carried out using keywords such as polymorphism and/or cancer and/or dietary carbohydrate and/or FTO gene." (PMID 31447604, 2019). "It seems that the association between the FTO gene and cancer cells is more tangible in hormone-dependent cancers." (PMID 31447604, 2019). "The probable molecular mechanisms of the association between the FTO gene and cancer development were also reviewed." (PMID 31447604, 2019). "The aim of this study was to assess the prevalence of risk factors of cardiovascular disease in patients treated for childhood cancer and to determine the involvement of clinical (cancer type or therapy) and/or genetic (FTO gene polymorphism) factors." (PMID 29675043, 2018). "Three meta-analyses have summarized the associations between FTO SNPs and risk of cancer; however, there are several limitations for them." (PMID 28881622, 2017). "The associations of FTO variants with cancer risk were estimated by calculating the pooled odds ratios and 95% confidence intervals by meta-analyses." (PMID 28881622, 2017). "Third, two of three from the same study team examined the association between each of two SNPs (rs8050136 and rs9939609) in/near FTO gene and cancer risk." (PMID 28881622, 2017). "Epigenetics and metabonomics should be paid more attention in order to solve how BMI modify the association between FTO SNP and cancer risk." (PMID 28881622, 2017). "Persistent hypomethylation of critical genes such as FTO are associated with the pathogenesis of diabesity, neurodegenerative diseases, and common cancers." (PMID 28933365, 2017). "Up to now, a total of 27 publications have examined the associations between FTO SNPs and risk of cancer." (PMID 28881622, 2017). "Other studies have investigated the association between FTO genotype and macronutrient intake, and we have previously in the Malmö Diet and Cancer Study (MDCS) observed a higher percentage of energy from protein for carriers of the A-allele." (PMID 23589710, 2013). "FTO’s demethylase function and its association with cancer has gained attention in recent years." (PMID 40722726, 2025). "Our analysis revealed that FTO rs9939609 had a certain correlation with an elevated cancer risk within the Asian demographic q vs. r (OR = 1.22, 95% CI = 1.07–1.39, p = 0.003); rq + qq vs. rr (OR = 1.18, 95% CI = 1.04–1.35, p = 0.011); qq vs. rr + rq (OR = 1.78, 95% CI = 1.39–2.27, p = 0.001)." (PMID 40391584, 2025). "Notably, FTO knockdown caused significant suppression of genes involved in “transcriptional misregulation in cancer”, which ranked at the top." (PMID 40435251, 2025). "Consequently, it is essential to perform a thorough meta‐analysis to assess how FTO gene polymorphisms affect cancer susceptibility." (PMID 40391584, 2025).
cancer (continued). "FTO has been reported to be upregulated in various tumors, and its elevated levels are independently associated with a decreased overall survival (OS) rate in various cancer patients." (PMID 41281757, 2025). "FTO rs9939609 showed a correlation with cancer risk among individuals of Asian descent." (PMID 40391584, 2025). "Consequently, further large‐scale case–control studies are necessary to investigate how FTO gene polymorphisms affect cancer susceptibility." (PMID 40391584, 2025). "Hernández‐Caballero ME and Sierra‐Ramírez JA conducted a comprehensive review in 2015 on the single nucleotide polymorphisms (SNPs) of the FTO gene and their associations with cancer risk, laying a solid foundation for understanding the genetic factors involved." (PMID 40391584, 2025). "Huang's meta‐analysis examined the association between the FTO gene polymorphism rs9939609 and cancer risk, offering robust evidence from a large population and highlighting the widespread nature of this polymorphism across various cancers." (PMID 40391584, 2025). "The relevant literature on the relationship between FTO variants and cancer susceptibility was comprehensively gathered from PubMed, Scopus, Embase, Medline, and Web of Science prior to May 20, 2024." (PMID 40391584, 2025). "Some studies have shown a relationship between FTO and cancer, where single nucleotide polymorphisms (SNPs) may have some impact on cancer risk." (PMID 39040764, 2024). "FTO, implicated in various cancer types, including GC, might influence the m6A modification status of transcripts related to vimentin expression, affecting their stability and translation." (PMID 38685125, 2024). "In addition, large-scale epidemiological studies have demonstrated the association of the FTO SNP risk genotype with the development of cancers such as breast, kidney, prostate, and pancreatic cancers, as well as leukemia, lymphoma and myeloma." (PMID 38491196, 2024). "Despite this, several FTO SNPs were linked to higher or lower risk of cancers." (PMID 39744011, 2024). "The FTO SNPs also regulate gene expression at large kilobases of distance that may be related to cancer susceptibility." (PMID 37471425, 2023). "Conversely, the loss of FTO function resulted in a reduced proliferation rate of cancer cells." (PMID 38094306, 2023). "According to reports, the m6A “writer” proteins methyltransferase-like 3 (METTL3) and METTL14, as well as the “eraser” protein obesity-associated protein (FTO), are intricately involved in the modulation of m6A methylation and the development of various cancer types." (PMID 37938417, 2023). "Certain FTO SNPs variations are strongly linked to susceptibility to cancers." (PMID 35422475, 2022). "Notably, recent pioneering studies have identified a significant association of FTO overexpression with the cancer progression of various types." (PMID 36497402, 2022). "Among m6A erasers, FTO has been associated with glutamine metabolism in cancer." (PMID 36289851, 2022). "In addition to that, SNPs of the FTO gene were also found to be associated with various types of human cancer, such as breast, colon, gastric, pancreatic, and prostate cancer." (PMID 35923209, 2022). "Recently some of variants at FTO gene have also been associated with development of cancer." (PMID 34837923, 2021). "While the FTO can contribute to the development of cancer through affecting several biochemical pathways, genetic association between rs9939609 polymorphism and the risk of developing cancers was reported." (PMID 34650918, 2021). "Loss of FTO in ICC correlates with cancer aggressiveness and poor prognosis." (PMID 32111216, 2020). "Recent studies showed that dietary macronutrients may have an impact on cancer by altering the expression level of the genes associated with the metabolism of cancer cells (such as FTO)." (PMID 31447604, 2019). "The possible mechanism behind the effect of the FTO gene on cancer risk has been studied recently." (PMID 31447604, 2019).
cancer (continued). "The association between the FTO gene expression and cancer risk was also recently identified." (PMID 31447604, 2019). "Further studies are necessary to clarify the underlying mechanism between FTO SNP and cancer risk." (PMID 28881622, 2017). "After adjustment for BMI, FTO rs9939609 SNP risk allele was associated with cancer risk in East Asian population (OR=1.29, 95%CI=1.06-1.57) and African population (OR=1.21, 95%CI=1.06-1.38), but not in European population, Middle East population and Mixed population (all P>0.05)." (PMID 28881622, 2017). "Therefore, we aimed to perform an updated meta-analysis to investigate the associations between FTO rs9939609 SNP (or any proxy SNP, r2>0.90) and other SNPs which are not in tight LD with rs9939609 SNP (such as rs1477196 and rs11075995) and cancer risk." (PMID 28881622, 2017). "Although the underlying biological mechanisms by which body fatness becomes a risk for cancer development are not fully understood, recent studies have shown that a set of single nucleotide polymorphisms (SNP) in FTO gene may associate with cancer risk." (PMID 26146447, 2015). "Additionally, FTO-mediated demethylation of m6A has also been shown to enhance cell viability and accelerate cell proliferation in acute myeloid leukemia cells, inhibit apoptosis in cancer cells, and increase the risk of infectious diseases." (PMID 40646842, 2025). "Hence, FTO polymorphisms could exert an influence on the hormonal balance and physiologic factors and might increase cancer risk." (PMID 37627102, 2023). "In addition to being associated with cancer, FTO is also associated with immunity." (PMID 36389678, 2022). "Hence, FTO expression is suspected to be a risk factor for several cancers as it could result in poorer prognosis and potentially affect therapeutic efficacy." (PMID 34650918, 2021). "Moreover, the polymorphisms in the FTO gene are associated with cancer and may exert their role through their influence on the expression of the effective genes in cancer." (PMID 31447604, 2019). "However, the link between FTO polymorphism, hormonal metabolism, and cancer risk is yet uncertain." (PMID 31007685, 2019). "Therefore, the FTO polymorphisms could exert an influence on hormonal balance and physiologic factors and might increase cancer risk." (PMID 31007685, 2019). "However, FTO rs9939609 variant was associated with some types of cancer in the subgroup analysis." (PMID 28881622, 2017). "Recurrent insertions were located near cancer-associated genes, including RB1, NEDD4, FTO, LAMA2, NOD1, and KCNB2, implicating LINE-1 activity in cis-regulatory remodeling of oncogenic pathways." (PMID 41681929, 2026). "Although further optimization and in vivo validation are required, this approach parallels recent advances in targeting RNA modification machinery, such as METTL3 and FTO, in cancer therapy." (PMID 41496500, 2026). "A recently reported FTO degrader, QP73, also induces FTO degradation and exhibits cancer cell killing activity in the nanomolar range." (PMID 40815637, 2025). "For example, FTO supports cancer (stem) cell growth and maintenance and the expression of immune checkpoint molecule PD-L1, thereby enhancing immune evasion." (PMID 40234389, 2025). "RNA modification enzymes, particularly RNA methyltransferases such as METTL3 and demethylases such as FTO, have emerged as promising therapeutic targets for cancer treatment." (PMID 40747121, 2025). "Targeted DNA sequencing was conducted on common FTO and ALKBH5 variants previously reported to be associated with cancer risk." (PMID 40361322, 2025). "This is not contradictory to the conclusion in previous studies that FTO promotes cancer through the Wnt pathway." (PMID 41145484, 2025). "For instance, while FTO acts as an oncogene in pNENs, studies have demonstrated its anti-cancer role in other cancers." (PMID 39990672, 2025).
cancer (continued). "Our findings highlight this FTO degrader as a valuable tool compound for elucidating the functional roles of FTO in cancer and as a potential foundation for the development of selective anticancer therapies." (PMID 40815637, 2025). "To date, more than 10 FTO inhibitors have been identified, and the therapeutic efficacy of these inhibitors has been evaluated across various cancers." (PMID 40823087, 2025). "In our study, transgenic mice, organoids and a metastatic xenograft model were used to investigate the role of FTO in cancer biology." (PMID 41184232, 2025). "In gastric and breast and cancer cells, increased FTO expression has been related to PI3K/AKT activation, whereas FTO suppression reduced PI3K/AKT signaling." (PMID 40429638, 2025). "Recent studies have demonstrated that FTO plays a critical role in the pathogenesis and progression of various cancers." (PMID 41145484, 2025). "FTO has been reported to repress the growth of cancers in the colon, liver, and stomach, while it has also been reported to promote cancer cell proliferation 34-40." (PMID 39897037, 2025). "Numerous methodologically similar studies subsequently identified FTO-targeted m6A sites in numerous other cancers and disease contexts." (PMID 41279954, 2025). "In this study, the anti-cancer effect of FTO is consistent with its function as an m6A demethylase—low expression of FTO enhances the m6A modification of PDK1 mRNA, thereby stabilizing PDK1 and activating the pro-cancer AKT/mTOR pathway." (PMID 41145484, 2025). "As a result, FTO’s role in cancer progression is continually being elucidated in various types of cancers and cell types." (PMID 40722726, 2025). "Entacapone, another FTO inhibitor, has demonstrated potential in reducing body weight and glucose levels, as well as in inhibiting the growth of various cancers." (PMID 40040878, 2025). "FTO’s role in cancer was likely due to its demethylation activity directed at N6-methyladenosine (m6A)." (PMID 40722726, 2025). "Here, we present the expression changes of m6A methyltransferases METTL3 and METTL14, as well as demethylases ALKBH5 and FTO, across seven of the most prevalent cancers worldwide according to the TCGA database." (PMID 40136363, 2025). "Dysregulation of m6A machinery, including methyltransferases (METTL3, METTL14), demethylases (FTO, ALKBH5), and m6A readers (YTHDFs, IGF2BPs), has been implicated in oncogenesis, immune evasion, and therapy failure in multiple cancers, including HNSCC." (PMID 41624157, 2025). "FTO, discovered as the first RNA m6A demethylase, is frequently dysregulated and plays significant roles in various types of cancers." (PMID 39773744, 2025). "R‐2‐hydroxyglutarate also demonstrates the ability to suppress FTO activity while serving an anti‐cancer role." (PMID 39779466, 2025). "These major studies have led to follow-up studies that used similar approaches to report that FTO demethylates functionally important m6A sites in different cancers and other disease contexts." (PMID 41279954, 2025). "FTO is upregulated in various cancers and contributes to tumor progression by influencing HIF-1 activity." (PMID 40102715, 2025). "In summary, FTO plays an oncogenic role in these cancers by regulating the expression of its target genes through m6 A RNA modification and its demethylase activity." (PMID 40483535, 2025). "Since the discovery of its role as an eraser, FTO has been the focus of research on various cancers, especially drug development." (PMID 41008545, 2025). "Recent studies have elucidated the m6A-dependent roles of FTO in tumorigenesis and cancer progression across various malignancies." (PMID 39773744, 2025). "Despite disagreements regarding the relationship between FTO and the autophagy pathway in cancer cells, two significant investigations showed the beneficial regulatory effect of FTO demethylase on autophagy." (PMID 41327199, 2025).